RNA5SP343 (RNA, 5S ribosomal pseudogene 343)
Synonyms: RN5S343
Gene: Ribosomal RNA gene on chromosome 11 (74,198,748 to 74,198,854, reverse strand). Ensembl gene ENSG00000284736.
Homologues: Orthologues: chimpanzee 5S_rRNA (99% identical), guinea pig 5S_rRNA (77% identical). Paralogues in human: RNA5S1 (84% identical), RNA5S10 (84% identical), RNA5S11 (84% identical), RNA5S12 (84% identical), RNA5S13 (84% identical), RNA5S14 (84% identical), RNA5S15 (84% identical), RNA5S16 (84% identical), RNA5S17 (84% identical), RNA5S2 (84% identical), RNA5S3 (84% identical), RNA5S4 (84% identical), and 26 more.